ATG16L1 (autophagy related 16 like 1)
Diseases named in the same sentence as ATG16L1 in open-access papers (continued):
Sharing a sentence is not in itself a finding about the gene and the disease.
cancer (36 papers, 2012 to 2026). A tumor composed of atypical neoplastic, often pleomorphic cells that invade other tissues. "The ATG16L1 rs2241880 G-allele is associated with progression of gastric premalignant lesions and cancer." (PMID 34965181, 2022). "To get a more precise evaluation of the correlation between ATG16L1 rs2241880 polymorphism and cancer susceptibility, we performed a meta-analysis of the association of all eligible studies." (PMID 31370304, 2019). "Several studies investigated the impact of the ATG16L1 rs2241880 polymorphism on susceptibility to cancer." (PMID 31370304, 2019). "Background and Objectives: Previous studies have investigated the impact of the ATG16L1 rs2241880 (Thr300Ala) polymorphism on individual susceptibility to cancer, but the conclusions are still controversial." (PMID 31370304, 2019). "Several studies that have investigated the relationship between the rs2241880 (Thr300Ala) polymorphism in ATG16L1 and several cancers among different ethnic populations have had conflicting outcomes." (PMID 31370304, 2019). "A review of these findings could lead us to the critical role of autophagy in tumorigenesis and the effects of the ATG polymorphisms, especially ATG16L1, in cancer development and metastasis." (PMID 38353395, 2024). "Therefore, for the first time, we aimed to conduct a meta-analysis of all available studies published to date to examine the impact of the ATG16L1 rs2241880 polymorphism on cancer susceptibility." (PMID 31370304, 2019). "The association between cancer and increases in CASP3, CASP8, and ATG12/ATG5/ATG16L1 is described in the sections titled “Apoptosis”, “Exocytosis”, and “Autophagy”, respectively." (PMID 41154660, 2025). "In fact, mice with functional autophagy even displayed a tendency to develop more dedifferentiated carcinomas, as we found more high-grade adenocarcinomas in Xbp1/Rnaseh2bΔIEC mice compared to Atg16l1/Xbp1/Rnaseh2bΔIEC mice." (PMID 41057521, 2025). "In fact, it appears that ATG16L2, which is overexpressed in several cancers relative to ATG16L1, impairs the conjugation process by competing with ATG16L1 for binding to ATG592." (PMID 35585060, 2022). "It reported that knockout of ATG12 sensitizes cancer cells to CTLs, whereas knockout of ATG5 or ATG16L1 together with ATG12 results in resistance of cancer cells to CTLs." (PMID 36230955, 2022). "Among mammal ATG proteins, Beclin-1, ATG5, ATG7, ATG12, ATG16L1 and LC3B are the most studied with respect to inflammation, and defects in autophagy are linked to many inflammatory diseases and cancer." (PMID 31969156, 2020). "A number of studies on the ATG genes relevance to human cancers showed that other ATG genes are also oncogenically associated, including ATG2B, ATG5, ATG9B, ATG12 and ATG16L1." (PMID 31969156, 2020). "Together, these analyses indicate ATG16L1 as an important prognostic marker of clinical response and cancer cell aggression." (PMID 30736412, 2019). "For example, catabolic fibroblasts harboring ATG16L1 increase tumor cell metastasis by >11.5-fold, despite the fact that genetically identical cancer cells were used." (PMID 23896568, 2013). "Additionally, targeting the ATG16L1 axis was effective in modulating autophagy and overcoming drug resistance in cancer." (PMID 38994020, 2024). "Our results did not support an association between the ATG16L1 rs2241880 polymorphism and cancer risk." (PMID 31370304, 2019). "To determine if somatic mutations identified in human tumor samples directly affected this critical interaction between ATG5 and ATG16L1, we next compiled a list of all somatic ATG5 coding-sequence mutations that have been identified across a multitude of human tumors and cancer cell lines." (PMID 31636955, 2019). "ATG16L1 is also involved in regulation of carcinogenesis in many cancers." (PMID 31370304, 2019). "The exact effect of the ATG16L1 rs2241880 polymorphism on the pathogenesis of cancer is not fully understood." (PMID 31370304, 2019).
cancer (continued). "Finally, we provide evidence that ATG16L2, which is overexpressed in several cancers relative to ATG16L1, hijacks the conjugation switch by competing with ATG16L1 for binding to ATG5." (PMID 31636955, 2019). "Abnormal expression levels of some human VPS34, ATG4A and ATG16L1 genes occurs in several types of cancer cells, which may be closely related to tumor progression, tumor suppression and cancer therapy resistance." (PMID 30460069, 2017). "Because the T84 is a cancer cell line, it contains a number of chromosomic alterations, one of which is the lack of one copy of chromosome 2, in which ATG16L1 is located." (PMID 38136224, 2023). "Three genes, WIPI2, ATG16L1, and GABARAPL1, showed comparable changes in various cancers." (PMID 34636718, 2021). "Furthermore, ATG16L2 is overexpressed in several cancers and competes with ATG16L1 for binding to ATG5 resulting in proteasomal degradation of ATG16L1 and disruption of autophagy." (PMID 34706732, 2021). "Our observations may indicate that ATG16L1 plays a regulatory role in the ATG16L complex because of its very limited expression in both normal and cancer tissue." (PMID 30374741, 2018).
tumor (36 papers, 2013 to 2026). "In parallel, ATG16L1 deficiency reduces tumor stem-like populations in vivo independently of adaptive immune pressure." (PMID 37741832, 2023). "ATG16L1 promoted stemness-associated transcriptional programs in the tumor and suppressed inflammation within the tumor microenvironment (TME)." (PMID 37741832, 2023). "We next asked which of the transcriptional changes observed in ATG16L1 deficient tumors implanted in vivo were truly tumor-intrinsic." (PMID 37741832, 2023). "For instance, ATG16L1 was associated with tumor invasion and metastasis through activation of Akt signaling." (PMID 35524319, 2022). "Loss of Atg16l1 did not impact basal growth of AKPS organoids in vitro, suggesting that tumor-intrinsic loss of Atg16l1 may elicit tumor-extrinsic mechanisms of disease control in vivo." (PMID 37741832, 2023). "Here the authors report that tumor intrinsic expression of the autophagy gene ATG16L1 is associated with resistance to anti-tumor immunity in preclinical CRC models and that elevated ATG16L1 expression predicts poor immunotherapy response in Kras-mutant CRC patients." (PMID 37741832, 2023). "Here, we demonstrate that high tumor expression of the core autophagy gene ATG16L1 is associated with poor clinical response to anti-PD-L1 therapy in KRAS-mutant tumors from IMblaze370 (NCT02788279), a large phase III clinical trial of atezolizumab (anti-PD-L1) in advanced metastatic MSS-CRC." (PMID 37741832, 2023). "We next asked how tumor-intrinsic loss of Atg16l1 impacts the hematopoietic tumor microenvironment." (PMID 37741832, 2023). "The expression of pERK, pAKT, pSTAT3, and pS6 was verified in primary tumor tissue from the ATG16L1::NTRK2 fusion-positive case." (PMID 39326005, 2025). "Screening for other molecular tumor-driving alterations revealed a novel ATG16L1::NTRK2 fusion, which contributed to oncogenicity by activating the MAPK and PI3K pathways." (PMID 39326005, 2025). "Screening formalin-fixed paraffin-embedded tumor material using an open-ended RNA sequencing panel revealed a novel in-frame autophagy related 16 like 1-neurotrophic receptor tyrosine kinase 2 (ATG16L1::NTRK2) fusion gene." (PMID 39326005, 2025). "BECN1, ELAVL1, and ATG16L1 were highly expressed in tumor tissues, while NCOA4, FTH1, FTL, SNCA, TNF, ATG7, and ZFP36 showed low expression levels." (PMID 39593730, 2024). "To focus strictly on tumor-intrinsic effects of ATG16L1, we performed bulk RNA-seq profiling on WT and Atg16l1 KO CRC organoids cultured in vitro." (PMID 37741832, 2023). "Single cell RNA sequencing of tumors and intratumoral myeloid cells revealed tumor-intrinsic and -extrinsic consequences of Atg16l1 deletion in CRC." (PMID 37741832, 2023). "Increased clearance of Atg16l1 KO tumors by cytotoxic lymphocytes and IFNγ, along with a persistently enhanced IFN-response gene signature in NSG mice prompted us to directly characterize the role of tumor-intrinsic ATG16L1 in regulating IFNγ signaling." (PMID 37741832, 2023). "Livers from mice administered WT CRC organoids displayed extensive disease burden 6 weeks after inoculation, whereas a minority of mice (<40%) administered Atg16l1 KO CRC organoids presented with only occasional tumor foci." (PMID 37741832, 2023). "Collectively, these data suggest that loss of Atg16l1 leads to a reduction of the goblet, Paneth, stem cell and proliferative pools in CRC organoids, potentially restraining tumor growth." (PMID 37741832, 2023). "Lastly, orthotopic implantation of CRC organoids demonstrated that ATG16L1 was also required for tumor growth in the colonic mucosa." (PMID 37741832, 2023).
tumor (continued). "Although tumor burden in the Atg16l1 KO group remained significantly decreased compared to the WT group (approximately a 2-fold difference in BLI signal after 4 weeks), all NSG mice administered with Atg16l1 KO CRC organoids presented with large tumor nodules." (PMID 37741832, 2023). "IF staining of the tumor sections for ATG16L1 (green fluorescence) indicated that the decreased expression of ATG16L1 induced by PAE-siRNA was more obvious than the other groups." (PMID 35524319, 2022). "The expression of ATG16L1 detected by IF (green fluorescence) was the weakest in PAE-siRNA group, which indicated that the knockdown of circMDK by PAE-siRNA suppressed the tumor growth through decreasing the expression of ATG16L1 in PDX model." (PMID 35524319, 2022). "J. iaranai Peantum reported that ATG16L1 protein was upregulated in tumour cell lines and promoted apoptosis in HepG2 cells." (PMID 35293027, 2022). "In gastric cancer, miR-874 can inhibit autophagy to regulate the MDR of tumor cells by targeting ATG16L1 and enhance the sensitivity of tumor cells to chemotherapy drugs." (PMID 35136409, 2022). "We also assessed LC3, ATG5, ATG16L1 and p62 protein expression levels in tumours derived from HepG2/miR-142-3p and HepG2/control xenografts after sorafenib therapy." (PMID 29472524, 2018). "Fibroblasts with a high expression of BNIP3 accelerated tumor growth, while overexpression of ATG16L1 showed constitutive activation of autophagy and increased tumor growth." (PMID 28930154, 2017). "In this study, firstly, TMEM74 was shown to increase autophagic flux in diverse tumor cell lines and interact with ATG16L1 and ATG9A to induce autophagy." (PMID 29048433, 2017). "Additional integrated in silico analysis suggests that rs78835907 tends to affect ATG16L1 expression, which in turn is correlated with tumor aggressiveness and patient prognosis." (PMID 26365175, 2015). "In addition, other autophagy-related proteins (ATGs), including ATG7, ATG9B, and ATG16L1, also play important roles in tumor suppression." (PMID 40231206, 2025). "From the results, we noticed that tumor cells highly expressed AUP1 significantly correlated with proliferation marker (MCM2, MCM6), PI3K-AKT-MTOR pathway (Akt1, TSC1, mTOR, Foxo1), and autophagy signaling (Atg3, Atg4B, Atg4D, Atg7, Atg9A, Atg16L1) in IDH wildtype tumor cells." (PMID 37029364, 2023). "ATG16L1 expression showed a positive correlation with tumor epithelial signatures and negative correlations with immune and stromal signatures, suggesting that the primary source of ATG16L1 expression was tumor cells." (PMID 37741832, 2023). "and GP cluster markers, and an increase in the expression of SS cluster markers, demonstrating that these are direct changes caused by the absence of ATG16L1 in tumor cells." (PMID 37741832, 2023). "Histological analysis showed a significantly decreased tumor area in the Atg16l1 KO group." (PMID 37741832, 2023). "CircMDK could serve as a potential tumor biomarker that promotes the progression of HCC via the miR-346/874-3p-ATG16L1 axis." (PMID 35524319, 2022). "ATG16L1, the current study target protein for expression analysis, is a member of the autophagy-related protein family with an activating role in the autophagy pathway; thus, it has a tumour-inhibitory role." (PMID 35723373, 2022). "However, statistically significant increases in ATG16L2 expression were observed, relative to ATG16L1, in 5 out of the 12 tumor types analyzed (p < 0.01)." (PMID 31636955, 2019). "The fact that ATG5 is selectively inactivated by somatic mutations and/or alternative mRNA splicing, and that ATG16L2 is transcriptionally overexpressed, relative to ATG16L1, in multiple tumor types, suggests that the inhibition of autophagy is indeed oncogenic." (PMID 31636955, 2019).
tumor (continued). "Additionally, immunostaining analysis showed that ATG5 and ATG16L1 expression levels were significantly decreased in the HepG2/miR-142-3p xenografts compared with the HepG2/control tumour xenografts after sorafenib treatment." (PMID 29472524, 2018). "Hence, the role of ATG16L1 isoform status in the regulation of tumor cell survival after a therapeutic intervention may likely play a key role patient survival." (PMID 40827882, 2025). "In the Atg16l1 KO group, there was a significant increase in the proportion of IFN responsive CRC cells, pointing to tumor-intrinsic immunosuppressive processes dependent on autophagy." (PMID 37741832, 2023). "We have observed reduced expression of ATG1, ATG5, and ATG16L1 as well as decreased LC3B and elevated p62 levels, suggesting a diminished basal autophagy in TGCT and a likely tumor-suppressive function of autophagy in the tumorigenesis of TGCT." (PMID 30245976, 2018). "Immunohistochemistry showed low levels of miR-20a targets (BECN1, ATG16L1 and SQSTM1) in tumor tissues." (PMID 28628113, 2017). "Similarly, the tumor-suppressive effects of ATG9B and ATG16L1 were found in cervical cancer and epithelial cell tumors, respectively." (PMID 40231206, 2025). "Among the fourteen ferritinophagy-related genes studied, ten exhibited significant differences between tumor and normal samples: NCOA4, FTH1, FTL, SNCA (all p < 0.0001), BECN1 (p = 0.031), ELAVL1 (p = 0.00023), TNF (p = 0.00074), ATG16L1, ATG7, and ZFP36 (all p < 0.0001)." (PMID 39593730, 2024). "Collectively, our results show that independent of tissue niche, tumor-intrinsic ATG16L1 profoundly limits immune-mediated control of CRC, whereas it has a relatively minor impact when tumors are grown in immunodeficient hosts." (PMID 37741832, 2023). "To better understand how ATG16L1 impacted phenotypic programming of cells in the tumor and its microenvironment, we performed transcriptomic profiling of tumors implanted in the livers of NSG mice, since optimal growth of Atg16l1 KO CRC organoids required immunodeficient hosts." (PMID 37741832, 2023). "With TMAs containing punches of 10 non-neoplastic testicular tissues retrieved from contralateral testicular biopsies of patients with TGCT and punches from 191 TGCT tumor patients, we employed immunohistochemical methods to stain for key autophagy regulators, ATG1, ATG5, and ATG16L1." (PMID 30245976, 2018). "Regarding tumor cell survival, the resistance to metabolic stress induced by TMEM74 overexpression was counteracted by ATG5, ATG7, ATG16L1, ATG3 and ATG10 deficiencies but not the BECN1 and ULK1." (PMID 29048433, 2017). "We surprisingly found that the deletion of Atg16l1 led to a significantly increased tumor prevalence in Atg16l1/Xbp1/Rnaseh2bΔIEC mice (no functional autophagy present to compensate for defective UPR) compared to Xbp1/Rnaseh2bΔIEC mice (autophagy compensates for the defective UPR) of the same age." (PMID 41057521, 2025). "Taken together, we conclude that in non-MSI CRC, patients with ATG16L1-low tumors may generate a more inflammatory microenvironment, thereby promoting a productive anti-tumor immune response upon checkpoint inhibition with atezolizumab." (PMID 37741832, 2023). "Since either upregulation of ATG16L2 expression or downregulation of ATG16L1 expression in human tumors should increase the competitive binding of ATG16L2 to ATG5, we calculated the ATG16L2:ATG16L1 mRNA expression ratio in normal and tumor samples from the TCGA mRNA datasets." (PMID 31636955, 2019).